SERPINB2 (serpin family B member 2)
Description:
Inhibits urokinase-type plasminogen activator. The monocyte derived PAI-2 is distinct from the endothelial cell-derived PAI-1.
Synonyms: PAI-2; PAI2; PLANH2; HsT1201; PAI
Tractability: Small molecule: it has a binding pocket of medium quality. Antibody: its Gene Ontology location is reachable by antibodies, with high confidence; UniProt places it where antibodies can reach, with medium confidence; UniProt predicts a signal peptide or a membrane-spanning region. PROTAC: its protein half-life has been measured.
Gene: Protein-coding gene on chromosome 18 (63,871,692 to 63,903,888, forward strand). Ensembl gene ENSG00000197632.
Subcellular location: Cytoplasm; Secreted, extracellular space
Pathways (Reactome):
Hemostasis: Dissolution of Fibrin Clot
Immune System: Gene and protein expression by JAK-STAT signaling after Interleukin-12 stimulation
Gene Ontology:
Molecular function: serine-type endopeptidase inhibitor activity
Biological process: fibrinolysis; negative regulation of apoptotic process
Cellular component: extracellular region; plasma membrane; cornified envelope; cytoplasm
Genetic constraint (gnomAD): Loss-of-function variants: 24 observed, 32.75 expected, observed/expected ratio (o/e) 0.73, 90% interval 0.53 to 1.03. The upper end of that interval is the gene's LOEUF score, 1.03, which puts it in group 4 of 6, group 1 being the genes least tolerant of losing a copy. Missense variants: 513 observed, 492.79 expected, observed/expected ratio (o/e) 1.04, 90% interval 0.97 to 1.12. Synonymous variants: 199 observed, 172.59 expected, observed/expected ratio (o/e) 1.15, 90% interval 1.03 to 1.3.
Homologues: Orthologues: chimpanzee SERPINB2 (98% identical), macaque SERPINB2 (95% identical), rabbit SERPINB2 (84% identical), pig SERPINB2 (80% identical), dog SERPINB2 (78% identical), guinea pig SERPINB2 (76% identical), mouse Serpinb2 (76% identical), rat Serpinb2 (73% identical). Paralogues in human: SERPINB1 (46% identical), SERPINB10 (46% identical), SERPINB6 (44% identical), SERPINB8 (43% identical), SERPINB9 (42% identical), SERPINB3 (41% identical), SERPINB4 (40% identical), SERPINB12 (38% identical), SERPINB11 (38% identical), SERPINB13 (37% identical), SERPINB7 (34% identical), SERPINC1 (32% identical), and 24 more.
Diseases named in the same sentence as SERPINB2 in open-access papers:
SERPINB2 is named in the same sentence as 201 diseases in open-access papers, as found by Europe PMC text mining. Sharing a sentence is not in itself a finding about the gene and the disease. The quoted sentences say what the papers report.
asthma (43 papers, 2012 to 2026). "SerpinB2 is expressed in airway epithelial cells in nasal polyps and asthma in association with Type-2 inflammation." (PMID 41142810, 2025). "The findings demonstrate that CDC167, POSTN, SEC14L1, and SERPINB2 exhibit potential as diagnostic markers and therapeutic targets for individuals with asthma." (PMID 38580753, 2024). "Although the P-score presents satisfactory risk prediction and discriminating ability, the association of the three other genes with asthma, except for SERPINB2, remains unverified." (PMID 35967302, 2022). "A persistent disease signature associated with IL-13 (CLCA1, POSTN, SERPINB2) was identified in peripheral airways in treatment-resistant severe asthma." (PMID 28045928, 2017). "Dysregulated SerpinB2 expression and SerpinB2 polymorphisms have been associated with a number of diseases including pre-eclampsia, asthma, periodontitis, lupus, and scleroderma." (PMID 26083412, 2015). "CST1, POSTN, CPA3, and SERPINB2 were key genes that potentially linked AR and asthma." (PMID 36733482, 2023). "For example, meta-analysis based on the results of sputum transcriptome sequencing of asthmatic patients identified SERPINB2 as a potential signature gene associated with asthma pathogenesis and miR-34b as a key miRNA that regulates the SERPINB2 gene expression." (PMID 35967302, 2022). "Also of interest is the fact that the classical T2 sign (CCLA1, POSTN, and SERPINB2) was associated with the two kinds of asthma analyzed, which is consistent with our previous published data." (PMID 33936056, 2021). "We also identified three highly upregulated proteins (with fold changes of over 25), FCGBP, ALOX15, and SERPINB2, which play critical roles in human allergy, immune responses, and asthma." (PMID 38732251, 2024). "The expression of hub genes, including CCDC167, POSTN, SEC14L1, and SERPINB2, was significantly lower in healthy donors (controls) compared to asthma patients." (PMID 38580753, 2024). "Other markers previously associated with type 2 inflammation in asthma, including CLCA1, SERPINB2, and SPDEF, were significantly (p < 0.0001) increased in the IL-13 treated HBEC compared to normal HBEC." (PMID 38706568, 2024). "Venn diagram analysis results demonstrated that CST1, POSTN, CPA3, and SERPINB2 were not only candidate genes in key modules but also DEGs in AR and asthma." (PMID 36733482, 2023). "Environmental pollutants, such as diesel engine exhaust particles, can promote the expression of the SERPINB2 gene in bronchial epithelial cells while inducing an asthma attack, and its expression level is significantly correlated with the severity of asthma." (PMID 35967302, 2022). "Seventy subjects (28 healthy control subjects and 42 asthma subjects) in datasets GSE4302 underwent unsupervised hierarchical clustering based on the microarray expression levels of SERPINB2, POSTN and CLCA1." (PMID 35550122, 2022). "In dataset GSE4302, subjects with asthma were divided into Th2-high and Th2-low groups according to the expression of the SERPINB2, POSTN and CLCA1 genes." (PMID 35550122, 2022). "The findings showed that the level of SERPINB2 mRNA in the model of asthma is downregulated while that of SLC4A1 mRNA and TAAR9mRNA is upregulated compared with those of normal mice." (PMID 35967302, 2022). "Based on our analysis, we identified mir-34b-5p and miR-449c-5p (members of the miR-34/449 family) as highest-ranked microRNAs involved in the regulation of FFL involving transcription factor SMAD4 and SERPINB2 hub gene in asthma." (PMID 32770056, 2020). "This is consistent with previous association of asthma severity and biomarker panel including SERPINB2 from PBMC and correlation of SERPINB2 expression in respiratory epithelial cells with atopic asthma severity." (PMID 31290545, 2019). "Many researches have validated the importance of SERPINB2 in asthma and its role in inflammatory and remodeling process." (PMID 31058187, 2019).
asthma (continued). "When two biomarkers were combined, the combinations of CHI3L1 + POSTN, IL10 + POSTN, IL-8 + PI3, and SERPINB2 + POSTN were good to discriminate severe from moderate–mild asthma, and of smaller importance was the grouping of IL-8 + POSTN." (PMID 29977241, 2018). "The IL-13 response signature (CLCA1, POSTN, SERPINB2) was also upregulated in the central airways in severe asthma compared to health, however, to a lesser extent compared to peripheral airways, and it did not attain significance." (PMID 28045928, 2017). "In recent years, genetic studies of bronchial epithelial cells have discovered several genes, such as protocadherin 1 (PCDH1), periostin (POSTN), serpin family B member 2 (SERPINB2), and chloride channel accessory 1 (CLCA1), associated with asthma phenotypes." (PMID 28725641, 2017). "CLCA1 and SERPINB2 were upregulated in severe asthma and also in peripheral airways suggesting the persistence of the IL-13 signature in this lung region." (PMID 28045928, 2017). "SerpinB2 was demonstrated to be upregulated in bronchial epithelial cells and could promote the T2 inflammatory response in asthma patients and mouse models." (PMID 41142810, 2025). "Studies have shown that SerpinB2 is significantly elevated in the bronchial epithelial cells of asthmatic patients and is associated with pivotal clinical markers, such as FEV1, FeNO, eosinophil counts and asthma severity." (PMID 41142810, 2025). "Recent studies demonstrated SerpinB2 could modulate allergic airway inflammation disease inflammatory responses as well as asthma and nasal polyps." (PMID 41142810, 2025). "The predictive value of the hub genes was assessed using ROC curves, and the aero under curves for CCDC167, POSTN, SEC14L1, and SERPINB2 were approximately 0.79, 0.87, 0.86, and 0.89, respectively, supporting their sensitivity and specificity in asthma diagnosis." (PMID 38580753, 2024). "Finally, CCDC167, POSTN, SEC14L1, and SERPINB2 were designated as the asthma hub genes because they were characterized by all three machine learning algorithms." (PMID 38580753, 2024). "The asthma patients were classified into T2-high asthma (n = 22), and T2-low asthma (n = 20) according to the relative expressions of type 2 signature genes, SERPINB2, CLCA1 and POSTN." (PMID 37152983, 2023). "Moreover, the expression level of CST1 was significantly positively correlated with the expression levels of POSTN, CPA3, and SERPINB2 in the bronchial epithelium of AR patients and in the nasal epithelium of asthma patients." (PMID 36733482, 2023). "In addition, the volcano plot showed that CST1, POSTN, CPA3, and SERPINB2 were significantly up-regulated in the bronchial epithelium of asthma and nasal epithelium of AR." (PMID 36733482, 2023). "We found key asthma-associated genes including the T2-high signature genes of CLCA1, POSTN, and SERPINB2 as well as those not previously asthma-associated (e.g., CST1 and Vanin genes—VNN1–3) to be potentially influenced by aberrant H3K27ac." (PMID 33362848, 2020). "Here based on the study it can be hypothesized that in asthma repression of miR 34b/449 regulates upregulation of SERPINB2 mediated via SMAD4 upregulation by an unknown direct or indirect regulatory process." (PMID 32770056, 2020). "It has been described, together with POSTN and chloride channel accessory 1, as a gene-signature for Th2 asthma and mainly IL-13 asthma phenotype, but until our knowledge, SERPINB2 protein expression has only been studied in broncoalveolar lavage (BAL) and never before at a peripheral level." (PMID 29977241, 2018). "Previously reported overexpressed (IL-10, MSR1, PHLDA1, SERPINB2, and CD86) and underexpressed genes (CHI3L1, CPA3, IL-8, and PI3) in severe asthma were analyzed by RT-qPCR in peripheral blood mononuclear cells (PBMCs)." (PMID 37445432, 2023).
asthma (continued). "Several asthma related genes were prioritized including SERPINB2 and CTSC genes, which showed functional relevance in multiple tissue/cell types and related to asthma pathogenesis." (PMID 37438356, 2023). "Approximately half of the asthma subjects (n = 22) with consistently high expression of a signature of Type 2 inflammation (SERPINB2, POSTN and CLCA1) were identified as Th2-high asthma, and 20 asthma subjects were identified as Th2-low asthma." (PMID 35550122, 2022). "PCR analysis of SERPINB2, SLC4A1, and TAAR9 genes, which also exist in the mouse model of asthma, was conducted to verify the accuracy of the results." (PMID 35967302, 2022). "It is found that the AUC values of SERPINB2, SLC4A1, TAAR9 in patients with asthma and normal people are 0.854, 0.819 and 0.688, respectively." (PMID 35967302, 2022). "A recent study found 5 hub genes (SERPINB2, SERPINB4, LTF, MUC5B, and CST4) related to the pathogenesis of asthma in bronchial and nasal cells." (PMID 36076228, 2022). "Asthma subjects were stratified into two subgroups, Th2-high, and Th2-low asthma, based on their expression of a three-gene signature of Type 2 inflammation: POSTN, SERPINB2, and CLCA1." (PMID 34088958, 2021). "As demonstrated by others, quantification of expression of the LAE asthma-related genes CLCA1, SERPINB2 and POSTN confirmed they were up-regulated in asthmatics vs controls." (PMID 34233672, 2021). "Candidate DEGs including SERPINB2, POSTN, and CLCA1 have already been reported to participate in asthma." (PMID 35126350, 2021). "Serine protease inhibitors (SERPIN) genes like SERPINB2 and SERPINB4 have an important role in asthma pathogenesis." (PMID 32770056, 2020). "Heterogeneity in the severe asthma samples was evaluated using the IL-13 disease signature (CLCA1, SERPINB2 and POSTN) and the gene expression marker for steroid response (FKBP5)." (PMID 28045928, 2017). "Allergic airways inflammation in asthma is characterized by an airway epithelial gene signature composed of POSTN,CLCA1, and SERPINB2." (PMID 28701525, 2017). "In asthma, the three-gene-mean of periostin, CLCA1 and serpinB2 correlated with FeNO (r = 0.75, p = 0.0002), blood eosinophils (r = 0.58, p = 0.003) and PC20 methacholine (r = -0.65, p = 0.0006), but not total serum IgE (r = 0.33, p = 0.1)." (PMID 23866775, 2013). "Meanwhile, SERPINB2 has been shown to correlate with FEV1, FeNO, peripheral and sputum eosinophils and asthma severity, and has been identified as a biomarker of T2 inflammation in asthma." (PMID 41511918, 2026). "SERPINB2 and POSTN are an epithelial gene signature for type 2‐high asthma." (PMID 35344278, 2022). "Th2-high asthma has three specific differentially expressed transcriptomic profiles, namely, periostin (POSTN), chloride channel regulator 1 (CLCA1), and serpin peptidase inhibitor, clade B, member 2 (SERPINB2), among which POSTN was found to be a more reliable surrogate marker for Th2-high asthma." (PMID 35406434, 2022). "New genes and protein biomarkers, including CHI3L1, IL-8, IL-10, MSR1, PHLDA1, PI3, and SERPINB2, were proposed to discriminate healthy control subjects from non-allergic asthmatic patients (T2-low) and to determine asthma severity." (PMID 33936056, 2021). "Both the six gene signature (6GS: CPA3, DNASE1L3, CLC, IL1B, ALPL, and CXCR2) and T‐helper 2 signature (TH2S: CLCA1, SERPINB2, and POSTN) are proposed as biomarkers in the identification of inflammatory phenotypes of asthma in induced sputum and epithelial brushings, respectively." (PMID 31903716, 2020). "In a recent work, new gene and protein biomarkers CHI3L1, IL-8, IL-10, MSR1, PHLDA1, PI3, and SERPINB2, were proposed to discriminate healthy control subjects from nonallergic asthmatic patients (T2-low) and to measure asthma severity." (PMID 31143187, 2019). "By using gene expression microarrays in adult asthmatic AEC, it was shown that serpinB2 is upregulated (3.5-fold in asthma vs controls), unlike in the present study in children." (PMID 28493984, 2017).
asthma (continued). "Using microarray profiling of airway epithelial cells, we previously identified a Th2-high molecular phenotype of asthma based on expression of periostin, CLCA1 and serpinB2 and characterized by specific inflammatory, remodeling, and treatment response features." (PMID 23866775, 2013). "Indeed, we found that targeting of DERs within asthma-SEs at SERPINB2 did not result in induction of gene expression." (PMID 33362848, 2020). "HEKs were chosen because they do not express some of the genes upregulated in asthma (CLCA1, POSTN, SERPINB2) and as such mirror expression of healthy BECs." (PMID 33362848, 2020). "Among the top genes are ones that have been previously related to asthma (e.g., APOE, CHI3L1, EGR1, MYH11, OXTR, SERPINB2, SOCS3) and corticosteroid-resistant asthma (e.g., FOS) though not necessarily in humans or via changes of the ASM." (PMID 26207385, 2015).
breast carcinoma (43 papers, 1991 to 2024). "Worthy, SERPINB2 expression has been significantly associated with prolonged survival, decreased metastasis, or decreased tumor size in patients with breast cancer." (PMID 38741146, 2024). "Our findings reveal that in vivo SerpinB2 deficiency delays breast cancer development and metastasis and decreases the differentiation of TAMs toward a protumorigenic M2 phenotype." (PMID 38956496, 2024). "SerpinB2 function remains paradoxical in breast cancer; SerpinB2 is associated with reduced metastasis and prolonged survival in patients with breast cancer and shows increased significance for a favorable prognosis." (PMID 38956496, 2024). "SerpinB2-deficient MMTV-PyMT mice (PyMTSB2−/−) were previously produced to explore the biological roles of SerpinB2 in breast cancer." (PMID 38956496, 2024). "There is a significant association between SerpinB2 level and survival; breast cancer cell-associated SerpinB2 is identified as an unfavorable prognostic indicator." (PMID 38956496, 2024). "The in vivo functions of SerpinB2 in tumor cells and tumor-associated macrophages (TAMs) during breast cancer development and metastasis remain elusive." (PMID 38956496, 2024). "Our previous studies on mammary tumors in age-matched PyMTWT and PyMTSB2-/- mice demonstrated that SerpinB2 loss delayed tumor onset and significantly reduced tumor incidence rate and volume in the 4th-5th glands in PyMTSB2−/− mice compared to PyMTWT mice." (PMID 38956496, 2024). "We show that in PyMTSB2−/− mice, SerpinB2 deficiency delays mammary tumor initiation, growth, and LN metastasis, which is accompanied by a decrease in CD206+M2 TAMs and an increase in NOS2+M1 TAMs." (PMID 38956496, 2024). "Our study demonstrates that SerpinB2 deficiency delays mammary tumor development and metastasis in PyMTWT mice, along with reduced sphere formation and migration abilities of tumor cells and decreased macrophage protumorigenic polarization." (PMID 38956496, 2024). "This study represents the first trial to analyze the consequences of SerpinB2 deficiency on tumorigenesis, tumor growth, and metastasis throughout the course of mammary cancer progression." (PMID 38956496, 2024). "We previously observed that SerpinB2 deficiency changes the expression of numerous genes, specifically those involved in the immunological and inflammatory response found in mammary tumors of PyMTSB2−/− mice." (PMID 38956496, 2024). "Transcriptome profiling using RNA-Seq was performed in mammary tumors of PyMT and SB2−/−;PyMT mice to obtain the DEGs, the genetic network, and understand how SerpinB2 deficiency affects delayed breast cancer development and metastasis." (PMID 35768767, 2022). "Mouse models of SerpinB2-deficient mammary tumors are useful for addressing various scientific questions regarding the in vivo functions of SerpinB2 during breast cancer progression." (PMID 35768767, 2022). "This study prepared SerpinB2-deficient mice and analyzed the differentially expressed genes (DEGs) to determine if loss of this protein delays mammary tumor progression." (PMID 35768767, 2022). "SerpinB2 was highly associated with metastasis risk in breast cancer by overexpression in the triple negative breast cancer subtype (TNBC) compared to the luminal subtype." (PMID 31590453, 2019). "Whereas high SerpinB2 was related to reduced survival in bladder cancer, endometrial cancer, and esophageal squamous cell carcinoma, low SerpinB2 has been associated with worse survival in breast cancer, hepatocellular carcinoma, and pancreatic cancer." (PMID 29207598, 2017). "High SerpinB2 levels were associated with reduced survival and increased lymph node metastasis in breast cancer patients." (PMID 28427146, 2017). "In our previous study, immunohistochemistry revealed that SerpinB2 protein is highly expressed in tumor cells in aggressive breast tumor tissue with the triple-negative subtype, and is associated with a short overall survival in breast cancer patients." (PMID 38956496, 2024).